LEP (leptin)
Diseases named in the same sentence as LEP in open-access papers (continued):
Sharing a sentence is not in itself a finding about the gene and the disease.
Hypertension (continued). "The G2/M transition pathway is known to be affected by leptin, a protein associated with hypertension." (PMID 25519357, 2014). "A similar regression model constructed for AH showed that leptin levels increased by 2.1 times the risk of hypertension in men (p = 0.003; odds ratio [OR] 2.1; confidence interval [CI] 1.3–3.6) and in women (p = 0.01; OR 1.75; CI 1.2–3.8)." (PMID 24981337, 2014). "Our studies also showed that the leptin/adiponectin ratio was associated with the hypertension phenotype, indicating that high leptin and low adiponectin would increase the likelihood of a subject being hypertensive." (PMID 23251471, 2012). "In the case of leptin an association remained with a hypertension phenotype which suggests that leptin has a more significant influence than adiponectin in this Saudi cohort." (PMID 23251471, 2012). "Significant associations have been found between plasma leptin levels and hypertension in both males and females, which makes leptin a potential predictor of hypertension." (PMID 21410966, 2011). "Previous studies have suggested a causal link between leptin levels in obese patients and the development of hypertension." (PMID 20509943, 2010). "Leptin has been shown to be linked to mean blood pressure in lean subjects with essential hypertension." (PMID 20066136, 2008). "The SBP correlated with measures of adiposity, hyperleptinaemia and hyperinsulinaemia, all of which may have contributed to the rise in blood pressure, but leptin specifically has been implicated in the development of adiposity‐related hypertension." (PMID 40538089, 2025). "Indeed, carotid bodies denervation inhibits BP increase induced by leptin infusion in lean and obese mice whereas the expression of leptin receptor in the carotid bodies leads to hypertension in leptin receptor–deficient db/db mice." (PMID 38186879, 2024). "High blood pressure and increased leptin levels are risk factors for atherosclerosis." (PMID 39796562, 2024). "There was a strong association between high blood pressure and AR, and it was also common comorbidity of AR, which may be related to higher concentrations of homocysteine and leptin, but the specific mechanism needs to be further studied." (PMID 38191356, 2024). "In a study that excluded women with chronic and preexisting hypertension, hypertensive disorder of pregnancy was associated with increased cord blood levels of adiponectin, leptin, and ghrelin after adjusting for gestational age, maternal age, and birth weight in preterm infants." (PMID 37764824, 2023). "An association has also been reported between leptin and arterial stiffness and hypertension." (PMID 37443807, 2023). "Both ADM and leptin display vasoprotective propeterties on the one hand, but are also related to cardiovascular risk factors beyond BMI and waist circumference, including arterial hypertension and vascular alterations on the other hand." (PMID 34990470, 2022). "The serum leptin level of hypertension patients is higher than that of healthy people, and there is a significant positive association between diastolic and systolic blood pressures and leptin level." (PMID 35346065, 2022). "The enhanced leptin plasma levels may augment blood pressure, promoting hypertension, which is an additional risk factor for AD." (PMID 34827650, 2021). "On the other hand, leptin activates the sympathetic nervous system and increases blood pressure, predisposing to hypertension." (PMID 34276408, 2021). "Chronic elevation in serum leptin levels during the prepubertal period tend to develop higher BMI z-scores and global metabolic risk scores, although risk for hypertension is low with a lower systolic blood pressure z-score in early adolescence, compared to those in the leptin-stable group." (PMID 33114326, 2020). "We and others have shown the significant association between the hormone leptin and hypertension." (PMID 33265898, 2020).
Hypertension (continued). "In the current study, the susceptibility to hypertension and renal injury were similar in female and male SSLepRmutant rats, which suggests that inhibiting leptin signaling may temper sex differences in the SS rats." (PMID 33071820, 2020). "By contrast, the LEP rs2167270allele was only significantly associated with CAD plus hypertension." (PMID 32049202, 2020). "Hypertension is not only associated with cardiovascular abnormalities in structure and function but also with dysregulated circulating levels of two important adipokines: leptin and adiponectin (APN)." (PMID 32566092, 2020). "Leptin was also associated with high blood pressure in men and hyperglycemia in both men and women." (PMID 33374992, 2020). "However, higher preconception leptin remained associated with an increased risk of GDM after controlling for either WHR or BMI while the association with hypertensive disorders was noted after controlling for WHR but attenuated when controlling for BMI." (PMID 32313676, 2020). "Recent studies from our group demonstrate that leptin increases adrenal aldosterone production, and increases serum aldosterone levels, in young obese female rodents which underlies the development of endothelial dysfunction and hypertension." (PMID 31262349, 2019). "Moreover, leptin has been associated to hypertension and congestive heart failure (HF) in humans, dogs, and cats." (PMID 31091785, 2019). "Moreover, the abnormal adipokines, including high leptin levels and high L:A ratio, showed an increased risk of developing hypertension when compared with individuals with normal adipokines." (PMID 29093301, 2018). "Compared with the normal adipokines levels, individuals with high leptin levels and a high L:A ratio demonstrated an increased risk of developing hypertension (RR 2.10; 95% CI, 1.19–3.73 and RR 2.19; 95% CI, 1.23–3.90, respectively), after adjustment for confounders." (PMID 29093301, 2018). "Moreover, weight was associated with increased risk of BPH and hypertension, weight combined with hypertension would resulted in regression of the gland volume via abnormal adipokine levels (such as leptin vs. adiponectin ratio)." (PMID 30319442, 2018). "In humans, a number of studies confirmed the association between leptin and hypertension." (PMID 28966594, 2017). "Elevated leptin stimulates Na+ retention and induces hypertension in rats and may be associated with hypertension induced kidney disease in humans." (PMID 28439255, 2017). "Furthermore, in the Copenhagen City Heart Study increased plasma leptin levels predicted the risk of developing hypertension." (PMID 28966594, 2017). "Several studies have shown that hypertension is associated with high plasma levels of leptin." (PMID 27746739, 2016). "In obese animals, the development of hypertension is associated with high leptin levels." (PMID 25793389, 2015). "Given the known pathogenic role of leptin/adiponectin in hypertension development, lower adiponectin and higher leptin in subjects with NAFLD may contribute to increase of blood pressure." (PMID 26618774, 2015). "Systemic hypertension may be associated with an increased pulmonary vascular resistance, which we hypothesized could be, at least in part, mediated by increased leptin." (PMID 24499246, 2014). "Leptin has been associated with hypertension and increased sympathetic autonomic activity." (PMID 25152707, 2014). "Altered pulmonary vascular reactivity in hypertension may be related to a loss of endothelial buffering of vasoconstriction and decreased leptin-induced vasodilation in conditions of increased endothelin-1." (PMID 24499246, 2014). "Whilst the role of TNF-α in hypertension risk appears apparent, it should also be stressed that other adipokines such as leptin, IL6, resistin, plasminogen activator inhibitor 1 (PAI-1) and adiponectin may also have a role." (PMID 23251471, 2012).
Hypertension (continued). "Additionally CRP (p<0.05), leptin (p<0.001) and leptin/adiponectin ratio (p<0.001) were also significantly associated with the hypertension phenotype." (PMID 23251471, 2012). "In addition to adiponectin, other adipocytokines, such as leptin, have also been linked with the development of hypertension." (PMID 19754934, 2009). "Clinical studies suggest an association between leptin and hypertension." (PMID 20066136, 2008). "Considering the sex-specific characteristics of fibro-calcific aortic valve disease, and given that hypertension is a critical risk factor for AS development, the insights on this adipokine (i.e., leptin) could be instrumental in deepening our understanding of aortic valve pathophysiology." (PMID 39335491, 2024). "Studies reported that hypoxia could lead to placenta leptin gene expression and production, and abnormal placenta leptin level was associated with aberrant trophoblast proliferation or invasion, as well as endothelial dysfunction, hypertension and fetal growth restriction, which may lead to PE." (PMID 38166707, 2024). "Also, FLI was more strongly related to adverse clinical outcomes and associated with masked hypertension than leptin or sOB‐R alone, suggesting that leptin and its receptor acting conjointly may be involved in the hypertensive disorders of pregnancy." (PMID 36950780, 2023). "However, this increase is remarkable in pre‐eclamptic pregnancies, suggesting that high leptin levels could contribute to the pathophysiology and underlying mechanisms of hypertensive disorders during pregnancy." (PMID 36950780, 2023). "Additionally, higher serum leptin levels at birth should predispose to increased blood pressure in adult rats since leptin is well known to be a relevant marker and mediator of vascular dysfunction and hypertension." (PMID 35706903, 2022). "Therefore, in addition to the relationship between hypertension and depression, it is speculated that poor nutrition, a contributing factor to low body weight, causes low levels of leptin and amino acids, resulting in more severe depressive symptoms." (PMID 36354390, 2022). "Increasing leptin levels, usually associated with anabolic status such as increased BMI and meals, can suppress satiety associated with weight-reduction and stimulate sympathetic activity which could induce hypertension." (PMID 21274292, 2009). "Of the given group, leptin and VEGF are characterized by the highest sensitivity, so the change in their serum levels will be visible as the fastest in people at high risk of hypertension." (PMID 41596212, 2026). "Leptin, IL-6, and VEGF presented the strongest correlation with hypertension, suggesting their potential in future diagnostic and preventive strategies." (PMID 41596212, 2026). "For example, these genes are present in several processes, including cellular metabolism, energy balance, and inflammation reduction, with LEP resistance leading to weight gain, cardiac inflammation, and hypertension." (PMID 40869172, 2025). "In animal studies, maternal consumption of a high-fat diet (HFD) has been shown to induce hypertension in offspring, accompanied by hypomethylation of the leptin gene promoter and elevated leptin expression in adipose tissue of exposed rat progeny." (PMID 41373994, 2025). "With respect to comorbidities, leptin concentrations were significantly elevated in patients with arterial hypertension (p = 0.003)." (PMID 40807227, 2025). "The development of hypertension in obese individuals has been attributed to several factors, including inflammation, leptin, and activation of the renin-angiotensin and sympathetic nervous systems." (PMID 40567975, 2025). "Albeit a small study sample with only n = 166 hypertensives and n = 66 masked hypertensive participants above 30 years of age, their findings suggest that leptin-related vascular impairment is similar to sustained and masked hypertension." (PMID 37872379, 2024).
Hypertension (continued). "In other words, increased plasma leptin levels, either through exogenous leptin administration or ectopic leptin overexpression, elevate blood pressure and heart rate, eventually leading to hypertension." (PMID 38397015, 2024). "For example, a human study showed an association between leptin gene variants and hypertension in postmenopausal women and a link between increased plasma leptin and hypertension in premenopausal women compared to men." (PMID 40988882, 2024). "Even blocking the glutamate receptor in postnatal period rescued some of the leptin-induced hypertension from regular feeding." (PMID 39323755, 2024). "The glutamatergic signaling network is as well involved in obesity-related hypertension, as the elevated BP induced by excessive central leptin was blocked by glutamatergic inhibition in mice fed a high-fat diet." (PMID 39323755, 2024). "Elevated leptin levels promote high blood pressure, platelet aggregation, inflammation, insulin resistance, and endothelial dysfunction." (PMID 40988882, 2024). "This notion is supported by the findings of high blood pressure and sustained increased levels of leptin in offspring through epigenetic memory in mothers fed with an HFD." (PMID 39796562, 2024). "Leptin, homocysteine production, and sodium retention also play a part in development of hypertension." (PMID 37418034, 2023). "Plasma leptin levels increase linearly with increasing body weight, and leptin induces hypertension and endothelial dysfunction using aldosterone-dependent methods." (PMID 36894988, 2023). "Leptin also appears to exert a critical effect in the enhancement of hypertension in obese pregnancy." (PMID 38138206, 2023). "In sharp contrast, obese females exhibit leptin (and insulin) resistance and are less likely to develop hypertension secondary to sympathoexcitation." (PMID 36769012, 2023). "Studies have found that the activation of renal sympathetic activity caused by leptin triggers RAAS activation, which leads to hypertension." (PMID 36985762, 2023). "A recent study showed that leptin acts on adrenocortical cells to increase CYP11β2 expression and directly activates aldosterone secretion which modulates hypertension in female mice." (PMID 36985762, 2023). "Previous studies have shown that high‐circulating leptin levels are present in animals and humans with hypertension." (PMID 36950780, 2023). "This is not a mere correlation but supported by evidence as lean individuals who received exogenous leptin exhibited hypertension." (PMID 35628271, 2022). "Aerobic exercise can significantly reduce the serum leptin level in PVAT in patients with hypertension and improve leptin resistance, and the adiponectin content increases." (PMID 35295586, 2022). "Specifically, in young obese men, leptin-derived sympathetic activation promotes hypertension, whereas premenopausal women develop hypertension through extra-sympathetic mechanisms." (PMID 36012601, 2022). "Leptin induces hypertension by increasing sympathetic outflow, decreasing nitric oxide (NO) production, and increasing endothelin-1 in endothelial cells." (PMID 36726470, 2022). "Leptin signaling has also shown to contribute towards hypertension in mice and rats, an effect mediated by angiotensin II." (PMID 35628271, 2022). "As a possible mechanism, in underweight females with hypertension, reduced leptin, increased blood pressure lifestyle, and a reduction in estrogen levels are synergistically associated with depressive symptoms." (PMID 36354390, 2022). "Elevated leptin levels, which often coincide with leptin resistance, are correlated with hypertension, myocardial infarction, and stroke." (PMID 36160851, 2022). "Leptin plays a role in the pathogenesis of hypertension, CAD, and type 2 DM and the development of their complications." (PMID 35207618, 2022).
Hypertension (continued). "As well, maternal HFD leads to offspring hypertension and was relevant to increased leptin promoter hypomethylation and leptin expression in adipose tissues of HFD-exposed rat offspring." (PMID 35897755, 2022). "Several studies confirmed the link between leptin and hypertension, reporting increased leptin levels in obese hypertensive individuals in comparison to obese normotensive subjects." (PMID 34068919, 2021). "Leptin has been related to increased activity of the sympathetic nervous system that contributes to hypertension, and leptin infusion in rats raised mean blood pressure." (PMID 33928108, 2021). "Leptin is also thought to contribute to the pathogenesis of hypertension by stimulating vascular inflammation, oxidative stress, and vascular smooth muscle dysfunction." (PMID 33431976, 2021). "We also examined leptin, an important biomarker and mediator of vascular dysfunction and hypertension, expression and methylation in adipose tissue and mesenchymal stem cells." (PMID 33431976, 2021). "It was also shown that ACE2 activation by XNT protected experimental pregnant rats against leptin induced hypertension and proteinuria and reduced hypertension-induced cardiac fibrosis in SHR." (PMID 33670126, 2021). "Astragaloside IV has an increase in the expression of α7nachr in hypothalamus and adipose tissue, which has inhibitory effect on the central and peripheral inflammatory response, and improves leptin resistance, which has a good effect on obese hypertension." (PMID 34840664, 2021). "Our group has shown that leptin acts in the leptin receptors in the carotid bodies to induce hypertension and to stimulate breathing and HVR." (PMID 34276408, 2021). "For example, the unhealthy-archetype was enriched for high BMI, its corresponding PRS, high levels of the protein leptin, and various other traits like high blood pressure, low levels of physical activity, and poor dietary habits." (PMID 34117230, 2021). "Hypertension and CB chemoreflex), we have also shown that leptin stimulates CB glomus cells and augments CSN activity through TRPM7 channels, elevating blood pressure." (PMID 32698380, 2020). "Studies have also shown a direct involvement of leptin in promoting hypertension-induced vascular hypertrophy." (PMID 32566092, 2020). "Central inhibition of AT1-R, TNF-α synthesis or microglial activation significantly attenuated either HFD- or leptin-induced upregulation of RAS activity, inflammation in the LT and PVN, and HFD or leptin sensitization of ANG II-induced hypertension." (PMID 32760236, 2020). "Experimental studies have shown that leptin induces hypertension and endothelial dysfunction in female mice via aldosterone-dependent mechanisms." (PMID 33182462, 2020). "Leptin is synthesized by VSMCs in response to forces that mimic hypertension and, in turn, induces VSMC hypertrophy." (PMID 32566092, 2020). "Leptin has been shown to be significantly different in the groups of obese patients with hypertension and patients with mildly elevated lipids." (PMID 32085704, 2020). "Weight gain, glucose intolerance, hypertension, abnormal adipocytokine levels, epigenetic changes in adipocytokines, leptin and adiponectin genes Changes in sperm miRNA profile and methylation status of germ cell, increased adiposity in future generation." (PMID 33511131, 2020). "In the group of children and adolescents with normal-weight hypertension, the correlation between ghrelin, leptin and adiponectin and anthropometrical parameters has also been found." (PMID 32085704, 2020). "Subgroup analysis of included patients revealed a moderate negative statistical correlation between ghrelin/adiponectin and a positive correlation between leptin and anthropometrical parameters in the group of obese children and adolescents with hypertension." (PMID 32085704, 2020). "POMC neurons have proven to be a key element of leptin-induced sympathetic activation and hypertension development." (PMID 32160920, 2020).